STK38 (serine/threonine kinase 38)
Diseases named in the same sentence as STK38 in open-access papers (continued):
Sharing a sentence is not in itself a finding about the gene and the disease.
cancer (continued). "To explore the expression difference of STK38 between cancer tissues and normal tissues, we used the TIMER2.0 web tool." (PMID 36232893, 2022). "The expression level of STK38 was significantly different between tumor and normal tissues in 15 types of cancers." (PMID 36232893, 2022). "Upon cell detachment, STK38 is necessary for the clearance of damaged mitochondria, prevention of an increase in the levels of reactive oxygen species, and protection of cancer cells." (PMID 34360836, 2021). "We further examined the effects of various stimuli on the expression and phosphorylation status of STK38 in human cancer cell lines and found that STK38 protein level decreased proportionally to the duration of hyperthermic treatment at 44 °C." (PMID 31690749, 2019). "As a protein kinase, STK38 represents a potentially interesting drug target to inhibit autophagy activity in Ras-driven cancers." (PMID 27283898, 2016). "More specifically, we define novel cancer cell biology roles of STK38 as a facilitator of pro-survival mechanisms in Ras-driven transformation." (PMID 27283898, 2016). "STK38 supports autophagy and mitophagy in detached Ras-transformed cells, thereby promoting cancer cell survival by facilitating anoikis resistance." (PMID 27283898, 2016). "Because STK38 is known to be a serine/threonine kinase possessing various roles in the cell cycle and cancer biology, we examined whether the kinase activity of STK38 is required for Ras-mediated acceleration of cell migration." (PMID 41226428, 2025). "STK38 is a Hippo pathway serine/threonine protein kinase with multifarious functions in cancers." (PMID 38082307, 2023). "We firstly performed a pan-cancer analysis of STK38 in this study." (PMID 36232893, 2022). "Second, the result showed that expression of STK38 was associated with immune cell infiltration and the clinical prognosis in cancers, we cannot verify whether STK38 may affect patient clinical endpoint by the immune pathways." (PMID 36232893, 2022). "Furthermore, previous studies have also demonstrated that STK38 participants in neurodevelopment, embryonic development, and cancer biology." (PMID 36232893, 2022). "Furthermore, the expression of STK38 was related to the infiltration of immune cells, such as NK cells, memory CD4+ T cells, mast cells and cancer-associated fibroblasts in a few cancers." (PMID 36232893, 2022). "In our study, we intended to perform a comprehensive analysis of STK38 in various cancers." (PMID 36232893, 2022). "Furthermore, the result in our study indicates that STK38 is negatively associated with infiltrating levels of CD4+ T cells, and it is positively correlated with NK cells and Mast cells in most cancer types." (PMID 36232893, 2022). "In addition to the transcription, we also used the UALCAN portal to assess the STK38 protein expression in different cancers based on the CPTAC dataset." (PMID 36232893, 2022). "In this regard, our data further propose that STK38-mediated removal of damaged mitochondria can play a role in preventing the increased production of ROS, which has the potential to significantly decrease cancer cell survival." (PMID 27283898, 2016). "It has also been reported that the knockdown of STK38 inhibits anoikis resistance, anchorage-independent soft agar growth, and in vivo xenograft growth of Ras-transformed human cells, shedding light on the supporting oncogenic role of STK38 in cell migration in Ras-dependent cancer cells." (PMID 41226428, 2025). "Furthermore, we found that STK38 plays a significant role in cancer immunity." (PMID 36232893, 2022). "Thus, our discovery of STK38 as autophagy regulator in Ras-transformed cells may help to develop an intervention opportunity for Ras-driven cancers." (PMID 27283898, 2016). "Thus, it will be interesting to ascertain in appropriate preclinical cancer models whether selective and acute STK38 inhibition can be of therapeutic benefit to target Ras-driven cancer cells without harming healthy tissues." (PMID 27283898, 2016).
cancer (continued). "Even more importantly, upon cell detachment STK38 is required to sustain the removal of damaged mitochondria by mitophagy, a selective autophagic process, to prevent excessive mitochondrial reactive oxygen species production that can negatively affect cancer cell survival." (PMID 27283898, 2016). "Here, we aim to provide an overview of current topics of STK38 in common mechanisms of regulation, DNA damage signaling, cross-talk between the DDR pathways, cancer, and the potential application for radiotherapy." (PMID 37046714, 2023). "STK38/NDR1 has recently emerged as a critical regulator of the cell cycle, development, apoptosis, and cancer." (PMID 37581937, 2023). "However, the correlation between STK38 expression and cancer immunity remains unclear." (PMID 36232893, 2022). "Moreover, HOXD8 was inversely related to serine/threonine kinase 38 (STK38) and MYC, two genes related to cancer progression." (PMID 39858044, 2025). "STK38 is implicated to suppress the transcription of ULK1, we then explored the expressions of STK38, ULK1 and p-ULK1 in the absence of Caprin-1 or/and STK38 cancer cells." (PMID 38082307, 2023). "Despite emerging biological experiments that are providing the correlation between STK38 and a few tumors, no pan-cancer analysis about STK38 in different cancers is available to date." (PMID 36232893, 2022). "A high STK38 expression was correlated with better OS and DFS prognosis in KIRC, which demonstrates that STK38 may serve as a protective factor in this cancer." (PMID 36232893, 2022). "Another interesting interacting protein of GRK5 is STK38 which is identified in GRK5 immunocomplex in cancer cell lines (MDA-MB-231 cells), but not in normal cells (HUVEC)." (PMID 22952844, 2012). "Although STK38 (serine-threonine kinase 38) has been proven to play an important role in cancer initiation and progression based on a series of cell and animal experiments, no systemic assessment of STK38 across human cancers is available." (PMID 36232893, 2022).
tumor (13 papers, 2016 to 2026). "Functional enrichment analysis of STK38-associated transcriptional signatures in pRCC revealed strong associations with gene programs related to tumor initiation and self-renewal, implicating STK38 as a potential regulator of intratumoral heterogeneity." (PMID 41540036, 2026). "We identified a phenomenon resembling tumor cell NETosis-like chromatin release (tNET release), which was markedly enhanced in STK38-deficient cells under stress." (PMID 41540036, 2026). "Collectively, these results indicate that low STK38 expression predisposes tumor cells to undergo tNET release under stress, potentially contributing to immune evasion and metastatic progression." (PMID 41540036, 2026). "Considering that STK38 was recently linked as a pro-apoptotic kinase to possibly tumour suppressive activities in adherent cells, we had hypothesized that STK38 might play a role in opposing Ras-mediated malignant transformation by promoting apoptosis in stress conditions." (PMID 27283898, 2016). "Extreme-limiting dilution assays further quantified the frequency of tumor-initiating cells, confirming that STK38 overexpression significantly enhanced tumorigenic capacity in vitro." (PMID 41540036, 2026). "For instance, STK38 has been reported to interact with components of the Wnt and Notch pathways—two key signaling axes involved in tumor progression." (PMID 41540036, 2026). "Future studies employing site-directed mutagenesis, live-cell imaging, and spatial multi-omics will be essential to fully define STK38’s regulatory logic and its dynamic role in tumor evolution." (PMID 41540036, 2026). "STK38 overexpression significantly promoted tumor growth, as expected, while GlaB treatment markedly suppressed tumor progression, with the most substantial reduction observed in the STK38-overexpressing group treated with GlaB." (PMID 41540036, 2026). "Our data suggest that STK38 promotes a self-renewing, undifferentiated tumor phenotype via selective activation of the Hh pathway, while also shaping the tumor microenvironment by modulating chromatin dynamics." (PMID 41540036, 2026). "Despite its broad involvement in various biological pathways, the functional dichotomy of STK38 in different tissues and tumor contexts remains poorly understood." (PMID 41540036, 2026). "Given its role in multiple signaling networks, STK38 is poised to serve as a crucial regulator of tumor heterogeneity, with potential implications for therapy resistance and disease relapse." (PMID 41540036, 2026). "Next, patients were separated into Caprin-1High and Caprin-1Low subgroups according to average expressions of Carpin-1 in tumor, the effects of STK38 and ULK1 on evaluating OS were explored in Caprin-1High patients." (PMID 38082307, 2023). "Caprin-1 activated autophagy through the interaction with ULK1 and STK38 that promoted tumor growth." (PMID 38082307, 2023). "STK38/STK38L kinases phosphorylate the transcriptional coactivator yes-associated protein (YAP1) and thereby negatively regulate YAP1 transcriptional activity, suggesting that STK38/STK38L function as tumor suppressors." (PMID 37046714, 2023). "On the other hand, STK38 provided a tumor suppressive capacity by phosphorylating YAP, thereby promoting its cytoplasmic retention and subsequent degradation." (PMID 36232893, 2022). "This revealed that STK38-depleted tumours displayed markedly decreased growth as judged by volume and weight." (PMID 27283898, 2016). "Notably, we observed that tNET release preferentially occurred in more differentiated, STK38-low subpopulations, suggesting a functional cooperation between phenotypically distinct tumor compartments." (PMID 41540036, 2026). "Collectively, these findings delineate a dual role for STK38 in pRCC—facilitating Hedgehog pathway-driven tumor initiation and cellular plasticity, while its downregulation predisposes tumor cells to NETosis-like chromatin release, potentially enhancing metastatic dissemination." (PMID 41540036, 2026).
tumor (continued). "Our findings are consistent with prior reports of STK38 enhancing cellular sensitivity to stress-induced apoptosis, suggesting that GLI1 inhibition may synergize with STK38-driven stress pathways to induce more effective tumor cell death." (PMID 41540036, 2026). "We hypothesized that STK38 downregulation sensitizes tumor cells to tNET release under stress conditions." (PMID 41540036, 2026). "Given the potential pro-metastatic consequences of STK38 inhibition, we instead targeted its downstream effector GLI1 using Glabrescione B, which potently suppressed tumor growth and induced apoptosis in both xenograft and patient-derived organoid models, particularly in STK38-high tumors." (PMID 41540036, 2026). "Emerging data suggest that STK38 may act as a central modulator of signaling pathways that govern tumor plasticity and differentiation." (PMID 41540036, 2026). "These interactions suggest that STK38 may function as a central regulatory hub coordinating multiple lineage-determining programs in tumor evolution." (PMID 41540036, 2026). "Notably, depletion of STK38 sensitizes tumor cells to a NETosis-like chromatin release process (tNET release), a form of stress-induced nuclear expulsion associated with immune evasion and metastatic potential." (PMID 41540036, 2026). "Although STK38 expression was not confined to a single dominant cluster, it was detectable across multiple tumor-associated clusters." (PMID 41540036, 2026). "This duality carries important translational implications: although STK38 suppression may limit the self-renewal capacity of tumor-initiating cells, it may also promote a pro-metastatic microenvironment by triggering tNET-associated chromatin release." (PMID 41540036, 2026). "Through a comprehensive series of in vitro, in vivo, and patient-derived organoid experiments, we identified STK38 as a critical modulator of tumor heterogeneity and demonstrated the therapeutic value of targeting its downstream effectors in STK38-high pRCC tumors." (PMID 41540036, 2026). "In this study, we observed that STK38 promoted Ras-induced cell migration and tyrosine phosphorylation of MerTK, suggesting that STK38 is most likely involved in Ras-induced cell migration and may facilitate tumor metastasis." (PMID 41226428, 2025). "Furthermore, we found that higher level of STK38 indicated poor prognosis in our dataset and TCGA database, suggesting that Caprin-1 promotes tumor growth through ULK1/STK38-dependent autophagy." (PMID 38082307, 2023). "Intriguingly, circCAPG can be translated into a polypeptide named CAPG-171aa which promotes tumor growh by disrupting the binding of serine/threonine kinase 38 (STK38) to SMAD-specific E3 ubiquitin protein ligase 1 (SMURF1) and thereby preventing MEKK2 ubiquitination and proteasomal degradation." (PMID 37408008, 2023). "To validate whether STK38 also has a critical function in promoting Ras-induced tumourigenesis in vivo, we injected HK-HRasG12V cells stably expressing control or STK38-targeted shRNAs as xenografts into nude mice and monitored tumour formation." (PMID 27283898, 2016). "Since autophagy is upregulated during metastasis, our findings further propose that STK38-mediated detachment-induced autophagy might contribute to metastasis by promoting anoikis resistance, which can facilitate tumour cell dissemination and dormancy." (PMID 27283898, 2016). "As a result, it is possible that STK38-mediated autophagy might help to meet the metabolic demands of Ras-transformed cells to facilitate the survival of tumour cells." (PMID 27283898, 2016). "However, as malignancy progresses and the need for maintaining tumor self-renewal capacity increases, STK38-high subpopulations may become more prevalent." (PMID 41540036, 2026).
tumor (continued). "Additionally, transcriptomic profiling of pRCC cells cultured under sphere-forming versus monolayer conditions showed consistent upregulation of stemness-related genes in STK38-overexpressing cells, further linking STK38 to the maintenance of undifferentiated tumor subpopulations." (PMID 41540036, 2026). "Moreover, by defining STK38 as a potential regulator of mitophagy, our study lays a foundation for follow up studies to increase our understanding of how mitophagy is initiated and executed as well as how mitophagy can play a role in Ras-driven tumours." (PMID 27283898, 2016). "STK38 is a member of NDR kinase family and plays a crucial role in tumorigenesis as a tumor suppressor or oncogene." (PMID 37408008, 2023). "To understand whether STK38 plays a role in Ras-mediated transformation of human cells, we initially selected HK-HT cells, since they are a well-defined cell system for studying Ras-driven malignant transformation by soft agar colony formation and xenograft tumour growth." (PMID 27283898, 2016). "In this study, we identify STK38 as a key regulator of tumor heterogeneity in pRCC, functioning through non-canonical activation of the Hedgehog (Hh) signaling pathway." (PMID 41540036, 2026). "In conclusion, our work establishes STK38 as a central coordinator of cellular plasticity and intratumoral heterogeneity in pRCC, and identifies GLI1 inhibition as a promising means of disrupting oncogenic self-renewal programs in aggressive tumor subsets." (PMID 41540036, 2026). "Previous studies demonstrate that STK38 and STK38L have redundant tumor suppressor function." (PMID 29108249, 2017). "Consistently, flow cytometric analysis using established surface markers CD24 and CD133 revealed that STK38 upregulation significantly increased the proportion of CD133+CD24+ double-positive cells in Caki-2 and ACHN cells, supporting its role in sustaining self-renewing tumor phenotypes." (PMID 41540036, 2026). "These high-STK38 cells may acquire the capacity to activate Hedgehog signaling through GSK3β and KIF7, thereby promoting the expansion of undifferentiated tumor subpopulations and enhancing tumor plasticity." (PMID 41540036, 2026). "Although the molecular mechanism by which STK38 contributes to the tyrosine phosphorylation of MerTK is not yet fully understood, our findings provide further understanding and imply a new target for tumor metastasis therapy." (PMID 41226428, 2025). "Notably, the expression of STK38 was not affected by the absence of NLRP12 in the tumor epithelium, suggesting that NLRP12 regulates the Wnt/β-catenin pathway through its interaction with STK38 but not the regulation of STK38 expression." (PMID 37581937, 2023). "Additionally, STK4 and STK38 are critical serine/threonine kinases regulating the cell cycle and apoptosis; they also exhibited an upregulation trend in the PTX+3-MA group, suggesting that 3-MA may induce tumor cell cycle arrest and apoptosis, thereby enhancing drug efficacy." (PMID 40649969, 2025).
infection (1 paper, 2022). The state of being infected such as from the introduction of a foreign agent such as serum, vaccine, antigenic substance or organism. "Meanwhile, previous study has demonstrated that STK38 may downregulate TLR9 signaling to decrease the inflammatory cytokine production and protect the host from an inflammatory injury during infection." (PMID 36232893, 2022).
metabolic disorders (1 paper, 2023). "The relevance of STK38 concerning metabolic disease is quite unexplored although its role has been implicated with cell cycle progression, apoptosis, autophagy, and transcriptional activity." (PMID 37028764, 2023). "Recent studies have implicated the role of STK38 in inflammation, but the relevance concerning the metabolic disease is quite unexplored." (PMID 37028764, 2023). "To explore the role of the NDR kinase family in metabolic disease, we chose STK38 as a representative." (PMID 37028764, 2023). "All these observations prompted us to explore the role of STK38 in metabolic disorders." (PMID 37028764, 2023).
STK38 also shares sentences with these, for which no sentence is quoted: colorectal cancer (3 papers); B cell lymphoma (2); pancreatic adenocarcinoma (2); Bellini duct carcinoma (1); breast carcinoma (1); cholangiocarcinoma (1); cocaine dependence (1); esophageal adenocarcinoma (1); Impaired glucose tolerance (1); kidney chromophobe (1); lung squamous cell carcinoma (1); melanoma (1); ovarian serous cystadenocarcinoma (1); prostate adenocarcinoma (1); renal carcinoma (1); skin cutaneous melanoma (1); spindle cell carcinoma (1); stomach adenocarcinoma (1); thymoma (1); thyroid carcinoma (1); urinary bladder carcinoma (1); uterine corpus endometrial carcinoma (1); Wilms tumor (1).